INS (insulin)
Diseases named in the same sentence as INS in open-access papers (continued):
Sharing a sentence is not in itself a finding about the gene and the disease.
Obesity (continued). "In particular, it has been demonstrated that the hypothalamic de novo ceramide synthesis plays a crucial role in central insulin resistance development and glucose homeostasis dysregulation associated with obesity." (PMID 36671568, 2023). "Changes in gut microbiota composition and functionality have been implicated in the onset and progression of obesity via modulation of energy metabolism, insulin sensitivity, and inflammatory signaling pathways." (PMID 37512528, 2023). "Declines in acyl‐carnitines also occur during HFD‐induced obesity and are associated with decreased insulin sensitivity." (PMID 37857571, 2023). "Obesity is a growing welfare concern in modern equine populations and predisposes horses to disturbances in energy metabolism such as insulin dysregulation." (PMID 37152686, 2023). "Elevated intestinal and plasma chymotrypsin levels associated with obesity and overeating have been correlated with increased insulin degradation, T2DM and cancer risk." (PMID 37233716, 2023). "Analysis of the muscle samples found eca‐mir106b to have a significant treatment effect, which has orthologs linked to obesity or muscle insulin response." (PMID 37324886, 2023). "This inflammatory state in WAT is a hallmark of obesity-induced metabolic dysfunction resulting in impaired glucose tolerance and insulin sensitivity." (PMID 38137473, 2023). "Basal lipolysis is increased, and β-adrenergic stimulated lipolysis is decreased in obesity, which is linked to excessive ectopic lipid deposition and insulin resistance." (PMID 36949095, 2023). "Functional and pathway enrichment analysis showed that miRNAs associated with obesity in this study were implicated in insulin signaling and insulin resistance biological pathways." (PMID 37987363, 2023). "Brain glucose hypermetabolism (during conditions of insulin clamp) appears as an early trait that characterizes subjects with obesity and subjects at an increased risk of obesity or prediabetes." (PMID 37512521, 2023). "Some studies link it to reduced appetite and weight loss via GPR41/43 interaction and enhanced insulin sensitivity, while others suggest its role in promoting obesity as a substrate for the liver and adipose tissue fat production." (PMID 38132864, 2023). "We also confirmed the expected obesity-associated rise in plasma insulin levels, which were approximately 257% higher in 14-week-old HFD-fed WT mice than in 10- to 12-week-old standard chow–fed WT mice." (PMID 38099492, 2023). "Because Cynara cardunculus contains multiple antioxidants, it likely participates in improving systemic insulin sensitivity by reducing the oxidative stress caused by the pre-obesity condition." (PMID 36678333, 2023). "GLP1RAs administration demonstrates substantial insulin sensitivity enhancement and profound weight loss effect and thus inhibits a vicious cycle among obesity, IR, hyperandrogenism, which promise its benefits in PCOS patients." (PMID 37940910, 2023). "Obesity, which is caused by long-term high-calorie consumption, can increase anxiety through insulin or leptin resistance, systemic inflammation, and hormonal dysregulation." (PMID 37926812, 2023). "In children with obesity, the brief intervention resulted in acute weight loss with lower fat mass and serum insulin." (PMID 38004223, 2023). "The first strike is characterized by increased intracellular triglyceride accumulation in hepatocytes due to adipose tissue lipolysis caused by obesity and insulin resistance." (PMID 37334291, 2023). "NAFLD is one of the complications associated with obesity, and is characterized by hepatic lipid accumulation, lipotoxicity, insulin resistance, gut dysbiosis and inflammation." (PMID 37674033, 2023). "The global prevalence of obesity continues to rise with the concomitant increase in the prevalence of type 2 diabetes resulting from the obesity-associated disruption of insulin action and β-cell function." (PMID 37773161, 2023).
Obesity (continued). "Obesity is associated with insulin insensitivity, so measures of obesity, such as body mass index and waist-to-hip ratio, are inexpensive methods that provide some insight into age-related changes in glucose and lipid metabolism." (PMID 37892346, 2023). "Commonly, obesity, hypertension, dyslipidemia, and altered insulin profile are well established cardiovascular risk factors in young adults." (PMID 36672887, 2023). "Obesity is strongly associated with insulin sensitivity in type 2 diabetes (T2D), mainly because free fatty acids (FFAs) are released from excess fat tissue." (PMID 37373436, 2023). "Obesity and aging are associated with impaired insulin-sensitivity, leptin-sensitivity, and nutrient-sensing in neurons within the ARC, which promotes increased food intake, hepatic gluconeogenesis, and adipocyte lipolysis." (PMID 37425648, 2023). "Recent studies have linked Lactococcus lactis to insulin resistance and systemic inflammation, exerting an anti-obesity effect." (PMID 37711887, 2023). "The pathogenesis of IR in PCOS is not completely clear, and apparently includes genetic and epigenetic changes, deficiency of insulin signal transduction, hyperandrogenaemia, obesity, and inflammation." (PMID 36631836, 2023). "Insulin sensitivity is maintained in mice that develop obesity as a consequence of collagen VI deficiency that results in unrestricted WAT expansion." (PMID 36782211, 2023). "Disruptions to this natural cycle have been associated with obesity, impaired insulin sensitivity, and altered lipid metabolism." (PMID 37445852, 2023). "Dysregulation of pulmonary adipocytokine/insulin signaling caused by early-onset obesity has been proven to induce asthma-like disease in mice." (PMID 37480069, 2023). "Since obesity and increased fat mass are strongly associated with these phenotypes, the abnormalities in insulin homeostasis in 12-month-old female Ob-Met offspring are likely secondary to the development of obesity." (PMID 36112170, 2022). "In androgen receptor deficient (ARKO) mice, late-onset obesity and fatty liver, as well as insulin- and leptin-resistance have been reported which is restricted to males." (PMID 35025875, 2022). "GDCA has been reported to be related to impaired insulin clearance which induced obesity-associated hyperinsulinemia." (PMID 36079806, 2022). "Increased ingestion of fats, obesity and resistance to hormones like insulin caused disturbances in normal cognitive function and structures as reported by our research team and others." (PMID 35508978, 2022). "Elevated iNOS expression occurs in obesity-induced hippocampal neuroinflammation, resulting in an abundant source of NO, which is linked to nitrosative stress, a potent obstructer of the insulin-signaling pathway in obesity." (PMID 36304965, 2022). "Mice with a paternal deletion of Nnat displayed decreased beta cell storage and secretion of mature insulin, hyperphagia and reduced energy expenditure, resulting in obesity caused by either aging or high-fat diet feeding." (PMID 35458198, 2022). "Cardiac dysfunction and myocardial injury observed in HFD-induced obesity are often associated with various molecular pathologies, represented by disturbed insulin-Akt signaling activation, namely myocardial insulin resistance." (PMID 35955507, 2022). "Insulin resistance caused by obesity is often accompanied by a transient increase in insulin secretion and the number of pancreatic β-cells as a compensatory mechanism." (PMID 35829914, 2022). "Second, another study suggested that reduced insulin sensitivity has been observed in people with circadian misalignment, and obesity is associated with reduced insulin sensitivity." (PMID 35276869, 2022). "As mentioned, in obesity there is typically a basal state of metaflammation associated with insulin and leptin resistance which derails if an acute inflammatory reaction becomes superimposed by infection." (PMID 35406000, 2022).
Obesity (continued). "Previous study reported that MED13 overexpression enhanced lipid metabolism, insulin sensitivity, and decreased susceptibility to obesity." (PMID 36685918, 2022). "As previous studies reported, obesity is associated with high levels of insulin, and women with endometrial cancer have an increased endometrial expression of genes involved in the insulin signaling pathway." (PMID 36313685, 2022). "In this context, cytokines such as TNF-α are produced and act on hypothalamic neurons, resulting in the inhibition of leptin and insulin signaling systems, causing obesity." (PMID 36290695, 2022). "Recent studies have shown that diets with a high insulin index are associated with increased odds of obesity in women." (PMID 36311488, 2022). "Obesity is characterized with elevated levels of fasting blood glucose and insulin, and is associated with insulin resistance and endothelial dysfunction." (PMID 35369299, 2022). "In the hypothalamic area, the inflammation produced by obesity was derived from a high-fat diet associated with weight gain and increased insulin resistance is related to the alteration in glial cells, causing hypothalamic astrogliosis." (PMID 36290695, 2022). "First, the effects of the obesity-related molecule TNFα and the insulin-sensitizer AdipoRon on molecules associated with the adiponectin signaling pathway in the in vitro model were evaluated." (PMID 35409282, 2022). "Together, these studies were crucial to indentifying the role of GSK-3 signaling in glucose metabolism, insulin signaling, and obesity-associated metabolic disorders." (PMID 35159367, 2022). "For instance, mice with Cdkn2a gene deficiency were protected against high-fat diet-induced obesity, had higher energy expenditure, and had better insulin sensitivity compared to Cdkn2a-normal mice." (PMID 35055468, 2022). "MKP-2 deficiency in mice protects against diet-induced obesity and hepatic steatosis and was accompanied by improved glucose homeostasis and insulin sensitivity." (PMID 35745205, 2022). "Of these, the SNP rs2867112 is near the protein-coding gene body TMEM18, and genetic variants in the proximity of the gene have been linked to obesity, insulin levels, and blood glucose levels." (PMID 35250867, 2022). "Increasing evidence indicates that high fructose diet causes various features of MetS such as obesity, adiposity, hypertension, hypertriglyceridemia, dyslipidemia, glucose intolerance, and decreased insulin sensitivity." (PMID 35782067, 2022). "These individuals would also be less prone to develop the proinflammatory status linked to obesity (determined by the macrophage M1), and therefore present with a better insulin-sensitivity profile." (PMID 36358463, 2022). "It is well established that obesity is associated with increased insulin secretion in humans and in obese animal models." (PMID 36143977, 2022). "Consistent with ITT results, the pAkt/Akt ratio was decreased in eWAT, liver, and muscle of CCL5 KO mice, indicating that CCL5 deficiency significantly attenuated insulin signal transduction in classic insulin target organs in obesity." (PMID 36713454, 2022). "In previous studies, we demonstrated that mice deficient in TSK exhibited remarkable resistance to high-fat diet–induced (HFD-induced) obesity and its associated metabolic disorders, including insulin resistance, adipose dysfunction, and hepatic steatosis." (PMID 35025761, 2022). "Secondly, in a published obesity GWAS, identified risk loci are highly associated with brain regions important for appetite regulation, learning, emotion, memory, insulin utilization, energy/lipid metabolism, and adipogenesis." (PMID 36556383, 2022). "This is because sex-hormone levels seem to be particularly associated with insulin amount, insulin sensitivity, and obesity, which in turn are strongly related to the MetS." (PMID 35629923, 2022).
Obesity (continued). "GDM is positively linked to other metabolic disorders, such as obesity, overweight, and type 2 diabetes, due to the similar pathways involved in glucose, lipid, and insulin metabolism." (PMID 36558427, 2022). "For example, the Zucker rat strain, which bears a mutation in the leptin receptor gene, is sugar metabolic deficient and insulin resistant and thus, serves as a spontaneous genetic obesity model." (PMID 35198334, 2022). "Certainly, given the pleiotropic effects of insulin, because of the altered glucose metabolism and the effects on lipid metabolism (insulin is an anabolic hormone), T2D is often associated with obesity." (PMID 36555364, 2022). "Most women with PCOS are metabolically insulin-resistant, in part due to genetic predisposition and in part to environmental factors such as obesity." (PMID 36139396, 2022). "Citrinin, the active ingredient in tangerine peels, has the effect of inhibiting obesity and can also improve insulin resistance by regulating the inflammatory response caused by obesity in adipose tissue." (PMID 36212945, 2022). "Chronic, morbid positive energy balance alters WAT functionality, renders it insulin-resistant, and induces its immoderate secretion of leptin, resulting in a loss of sensitivity of the hypothalamus to this hormone in obesity." (PMID 35741001, 2022). "Several animal models have shown that reduced hepatic insulin clearance occurs as an early homeostatic mechanism causing hyperinsulinemia during obesity." (PMID 36009446, 2022). "Among the most important proposed mechanisms linking obesity and cancer are obesity-induced low-grade inflammation and obesity-associated dysfunction of insulin/IGF1 signaling." (PMID 36320063, 2022). "Circulating levels of BCAA have been associated with obesity and insulin-resistant states through impaired protein anabolism and impaired insulin signaling." (PMID 36361016, 2022). "AAV-mediated LRG1 overexpression in the adipose tissues led to a constellation of metabolic effects in both B6 and db/db mice, resulting in improvement of glucose/insulin tolerance as well as a reduction of obesity-associated inflammation." (PMID 36346018, 2022). "Excess insulin causes sodium retention, blood volume expansion, and the production of norepinephrine in the body, resulting in hypertension in individuals with obesity." (PMID 36249655, 2022). "Higher serum levels of adiponectin have been reported to have a protective effect against cardiovascular risks and was associated with preserved insulin sensitivity in children with obesity." (PMID 36072927, 2022). "Note that sleep disturbances increase morning cortisol levels and reduce both insulin sensitivity and growth hormone secretion, supporting the association between poor sleep quality and obesity." (PMID 36211495, 2022). "Studies have shown that the loss of JNK1 can promote the reduction of obesity, the significant improvement in insulin sensitivity, and the enhancement of insulin." (PMID 35509833, 2022). "This is in direct contrast to our recent evidence indicating that elevated insulin secretion was more closely associated with hyperinsulinaemia than low hepatic insulin clearance in Black South African women with obesity." (PMID 36166072, 2022). "Obesity is considered a medical condition caused by eating more calories than necessary, but it can also be caused by a decreased response to insulin." (PMID 35731214, 2022). "Low insulin levels and IR are thought to be protective factors against obesity-associated complications." (PMID 35525976, 2022). "In obesity, skeletal muscle accumulates lipids caused by an imbalance of nutrient supply and utilization, with lipotoxic effects on insulin sensitivity." (PMID 35789435, 2022). "Energy adaptations in response to RYGB bariatric surgery in people with severe obesity were associated with changes in insulin, leptin, adiponectin, T3, intestinal hormones, and SNS activity." (PMID 36349055, 2022).
Obesity (continued). "Sedentary behavior and screen time levels, on the contrary, are associated with risk factors for chronic diseases, such as obesity, high fasting insulin levels, and metabolic syndrome during adolescence." (PMID 36187629, 2022). "Obesity is associated with decreased endothelial NO production, decreased insulin-stimulated vasomotion, and reduced capillary density, leading to impaired insulin-mediated capillary recruitment and microvascular dilatation." (PMID 35055038, 2022). "This is due, in part, to the fact that significant changes in brain insulin action have been linked to dementia and brain aging in addition to obesity and T2DM." (PMID 36505102, 2022). "Nevertheless, studies have shown that the deletion of JNK1 and IKKβ in neurons can rescue leptin and insulin signaling in the hypothalamus, as well as reduce weight gain and restore the metabolic alterations linked to obesity." (PMID 35112705, 2022). "Despite its potential role in obesity prevention, such approach has a great risk of preventing adipogenesis, which is required to maintain adipose tissue homeostasis and insulin sensitivity." (PMID 36232443, 2022). "Macrophages are associated with metabolic complications to obesity including fatty liver disease and impaired hepatic and muscle insulin sensitivity (IS)." (PMID 35040267, 2022). "Research showed that chronic inflammation associated with obesity impairs insulin signaling pathways and lipid metabolism." (PMID 36411989, 2022). "The obesity epidemic now affects a significant portion of the world, causing insulin resistance and metabolic dysregulation in multiple organs of the body." (PMID 35991189, 2022). "Its distribution is possibly altered, as well as β-cells function and insulin sensitivity, generally—to a greater extent the first and less the second—with respect to the much more common T2D associated to obesity." (PMID 36614099, 2022). "Multiple mechanisms were proposed to explain the risk correlation between overweight/obesity and EC, such as sex hormone metabolism, insulin and insulin-like growth factor signaling, and adipokine pathophysiology." (PMID 36291808, 2022). "VAT Tregs are functionally specialized tissue-resident cells that prevent obesity-associated inflammation and maintain insulin sensitivity and glucose tolerance." (PMID 36685567, 2022). "The acute phase protein CRP is secreted during cell injury or microbial infection is found to be associated with obesity, and its high concentration in blood leads to insulin insensitivity towards blood glucose." (PMID 36078079, 2022). "We assessed the expression of Mfn1 and 2 in islets isolated from the leptin receptor deficient db/db BKS mouse model, which develops obesity, progressive β-cell mitochondrial and insulin secretory dysfunction, and eventual β-cell failure." (PMID 35487893, 2022). "Obesity is associated with an increased number of classical inflammatory Ly6Chi blood monocytes that positively correlates with fasting insulin levels in the mouse." (PMID 36555392, 2022). "Other obesity–cancer association mechanisms include obesity-induced chronic inflammation; increased aromatase expression, circulating levels of estrogen, insulin, leptin and ceruloplasmin; and decreased amounts of adiponectin and sex-hormone-binding globulin." (PMID 35741001, 2022). "Obesity and chronic states of excess insulin are implicated in carcinogenesis through the PI3Kinase pathway and excess unopposed estrogen." (PMID 36117808, 2022). "The UCP2 uncoupler appears to be an important negative regulator of β-cell insulin secretion on the periphery, suggesting its role in the loss of glucose responsiveness in obesity-related T2DM." (PMID 35052794, 2022). "Inflammation can be associated with an increase of insulin resistance, as it has been shown that inflammatory signals generated as a result of obesity work to activate serine kinases that, in turn, impact and block insulin action and function." (PMID 35711466, 2022).